NLRP3 (NLR family pyrin domain containing 3)
Diseases named in the same sentence as NLRP3 in open-access papers (continued):
Sharing a sentence is not in itself a finding about the gene and the disease.
atherosclerosis (continued). "Recently, the molecular complexes called nucleotide-binding oligomerization domain-like receptor (NLR) family, pyrin domain containing 3 (NLRP3) inflammasomes have emerged as a key player for the crystal-induced inflammation in atherosclerosis." (PMID 29259717, 2017). "For one thing, CHC can enhance vascular wall inflammatory responses and lead to atherosclerosis by active NLRP3 inflammasomes, which regulate caspase-1 activation and subsequent processing of pro-IL-1β, triggering IL-1 secretion." (PMID 29133791, 2017). "Intriguingly, NLRP3 depletion dampens the severity of atherosclerosis, multiple sclerosis, Alzheimer’s disease, type 2 diabetes, and gout." (PMID 29375379, 2017). "The NLRP3 inflammasome senses crystalline danger signals that can occur during autoinflammatory diseases, such as gout or atherosclerosis, and environmental diseases, such as silicosis or asbestosis." (PMID 29403480, 2017). "Here, we review the current knowledge regarding the role of NLRP3 inflammasomes in the progression of atherosclerosis and the prospects for therapeutic approaches targeting NLRP3 inflammasomes." (PMID 29259717, 2017). "NLRP3 inflammasomes are essential for the initiation of vascular inflammation during the progression of atherosclerosis." (PMID 29259717, 2017). "The effect of IL-27 on NLRP3 inflammasome activation in monocytes, a pro-inflammatory mediator of atherosclerosis, was also very recently described." (PMID 29176764, 2017). "IL-18, as a member of IL-1 family, is regulated by the activation of NLRP3 inflammasome and has been proved to play a pro-inflammatory role in the pathogenesis of atherosclerosis." (PMID 28950870, 2017). "Further research is warranted regarding the effect of colchicine on the NLRP3 inflammasome in vitro and in vivo and its role in the pathogenesis of atherosclerosis and pancreatic inflammation." (PMID 28950870, 2017). "Activation of lysosome biogenesis by overexpression of TFEB, which regulates lysosome and autophagy-related genes, inhibits NLRP3 inflammasome activation induced by cholesterol crystals and attenuates the progression of atherosclerosis." (PMID 29259717, 2017). "Activation of NLRP3 inflammasome is an important step in the progression of atherosclerosis-related inflammation." (PMID 27110561, 2016). "P2X7R activation can also activate the NLRP3 inflammasome to promote the progression of atherosclerosis." (PMID 27777559, 2016). "Recent studies have confirmed that NLRP3 inflammasome is involved in inflammatory response during the pathogenesis of atherosclerosis." (PMID 28104929, 2016). "The aim of the present study was to investigate the role of P2X7R in atherosclerosis and the mechanisms of action of the NLRP3 inflammasome following stimulation with oxidized low-density lipoprotein (oxLDL)." (PMID 25761252, 2015). "This suggests that the high expression levels of P2X7R and NLRP3 in macrophages are involved in the progression of atherosclerosis." (PMID 25761252, 2015). "Activation of the NLRP3 inflammasome and hypersecretion of IL-1β are known to be involved in a variety of acute and chronic disorders including diabetes, atherosclerosis, gout, chronic kidney disease and Alzheimer’s disease." (PMID 25655831, 2015). "In conclusion, our results demonstrate that P2X7R plays a significant role in the development of atherosclerosis and regulates NLRP3 inflammasome activation by promoting PKR phosphorylation." (PMID 25761252, 2015). "Our group also recently demonstrated the importance of NLRP3 inflammasomes in neointimal formation after vascular injury, atherosclerosis, myocardial ischemia-reperfusion injury, and chronic renal disease." (PMID 25486008, 2014). "Cholesterol crystals are also sensed by NLRP3, which contributes to chronic vascular inflammation and ultimately the development of atherosclerosis." (PMID 24367371, 2013).
atherosclerosis (continued). "The nucleotide-binding domain, leucine-rich-containing family, pyrin domain-containing-3 (NLRP3) inflammasome has emerged as an important regulator of inflammation in metabolic disorders and atherosclerosis." (PMID 23825667, 2013). "NLRP3 activity has been demonstrated in a wide variety of other diseases, including Alzheimer’s disease, asbestosis and silicosis, gout, and atherosclerosis." (PMID 23840644, 2013). "NLRP3 activation is also enhanced in many age-related diseases, e.g. atherosclerosis, obesity and type 2 diabetes." (PMID 22411934, 2012). "Recently, the NLRP3 inflammasome has been identified as a central regulator of atherosclerosis pathogenesis." (PMID 23087690, 2012). "Consequently, cholesterol accumulation blocks further efferocytosis, activates the NLRP3 inflammasome, seeds cholesterol crystals, and drives foam-cell apoptosis that accelerates atherosclerosis." (PMID 41035425, 2026). "Taken together, these data demonstrate that Orientin, which alleviates HAEC inflammation and pyroptosis through regulating the MARCH8/NLRP3 axis, might be a potential candidate for treating diabetes-accelerated atherosclerosis." (PMID 41891145, 2026). "Notably, NLRP3 deficiency (DKO) nearly completely abolished plaque formation, indicating that NLRP3 is a key contributor to atherosclerosis." (PMID 41309549, 2025). "However, as an inflammatory disease, the role of NLRP3 in the pathogenesis of atherosclerosis has been widely investigated." (PMID 41272654, 2025). "Interestingly, ZL effectively alleviates vascular endothelial cells in atherosclerosis by regulating the miR-30b-5p/NLRP3 axis and significantly reduces the AS-related mRNA expression levels of NLRP3, ASC, Caspase 1, IL-1 β, and IL-18." (PMID 40373162, 2025). "However, when cholesterol becomes overloaded, it can aggregate into crystals that activate the NLRP3 inflammasome, a crucial driver of atherosclerosis." (PMID 41180526, 2025). "Among these, DCA enhances endothelial inflammatory responses by activating the NLRP3 inflammasome, while the weakened inhibitory effect of LCA on NLRP3 further exacerbates endothelial damage, collectively promoting early pathological changes in atherosclerosis." (PMID 41480102, 2025). "The activation of the NLRP3 inflammasome leads to the cleavage of procaspase-1 into active caspase-1, which in turn promotes the maturation and secretion of proinflammatory cytokines that contribute to atherosclerosis." (PMID 40966231, 2025). "Thus, CMA-lysosomal degradation of NLRP3 plays a crucial role in reducing NLRP3 protein levels, which, in turn, helps to limit inflammation and atherosclerosis progression." (PMID 40244103, 2025). "The NLRP3 inflammasome is predominantly activated in atherosclerosis by oxLDL." (PMID 39936975, 2025). "Moreover, NLRP3 inflammasome activation serves as a key amplifier connecting metabolic disorders to atherosclerosis inflammation." (PMID 41562048, 2025). "The NLRP3 inflammasome-activated products IL-1β and IL-18 mediate monocyte/macrophage aggregation and vascular endothelial cell expansion, both of which are important factors in atherosclerosis pathogenesis." (PMID 40830103, 2025). "It has been shown to inhibit the TLR4/NF‐κB/NLRP3 pathway, a key receptor in the Toll‐like receptor family that mediates LPS‐stimulated tissue damage, apoptosis, and inflammation, thus protecting VECs and preventing thrombosis and atherosclerosis progression." (PMID 40634132, 2025). "Similarly, impaired mitophagy facilitates NLRP3 inflammasome activation in atherosclerosis, and in silica nanoparticle exposure-induced cardiac adverse events, defective autophagic flux permits cytosolic mtDNA accumulation and cGAS-STING-mediated pyroptosis." (PMID 41009042, 2025). "TMAO activates NLRP3 through multiple mechanisms and facilitates the onset of atherosclerosis." (PMID 40278349, 2025).
atherosclerosis (continued). "Studies in atherosclerosis-prone mice demonstrated that deficiency of NLRP3, AIM2 (absent in melanoma 2), or gasdermin D in hematopoietic cells was associated with a reduction in overall atherosclerotic lesion size." (PMID 40076813, 2025). "In light of studies showing that FOXP1 can transcriptionally repress the NLRP3 inflammasome and inhibit the development of atherosclerosis, we hypothesized that CtBP1 might interact with FOXP1 to modulate VCAM‐1 and ICAM‐1 gene transcription." (PMID 39949978, 2025). "However, excessive triggering of the NLRP3 inflammasome can directly contribute to multiple inflammatory diseases, including sepsis, atherosclerosis, Parkinson’s disease, type 2 diabetes, multiple sclerosis, and cryopyrin-associated periodic syndromes (CAPS)." (PMID 41231359, 2025). "Most of the proposed interventions are expected to cause direct or indirect inhibition of the nucleotide‐binding domain leucine‐rich repeat and pyrin domain containing receptor 3 (NLRP3)‐IL‐1β/‐IL‐6 axis, because there is strong evidence for its involvement in atherosclerosis." (PMID 41182006, 2025). "Collectively, our findings provide novel mechanistic insights into the therapeutic role of PEMFs in atherosclerosis, highlighting that PEMFs can inhibit the progression of atherosclerosis by improving membrane tension and ultimately downregulating NLRP3 inflammasome expression." (PMID 41309549, 2025). "This is important since Yap1 is also considered a pathological marker in various inflammatory diseases, including atherosclerosis (e.g., Yap1 suppression is connected to NLRP3 inflammasome inhibition) and osseotendinous inflammation (e.g., Yap/Hippo pathway is linked to excessive tenascin)." (PMID 40583463, 2025). "A deeper understanding of their crosstalk and decisive impact on plaque stability not only expands our knowledge of atherosclerosis mechanisms but also lays a foundation for novel interventions—such as enhancing efferocytosis, inhibiting the NLRP3 inflammasome, or applying magnesium-based materials." (PMID 41562048, 2025). "Therefore, interventions targeting NLRP3 inflammasome activation are critical for attenuating atherosclerosis." (PMID 41277959, 2025). "Moreover, using the atherosclerosis model ApoE−/− mouse, the NLRP3 inflammasome emerges as a central target in the fight against ED and CVDs, as evidenced by recent studies highlighting various therapeutic strategies." (PMID 40227195, 2025). "ZL, in combination with atorvastatin, can inhibit the activation of the NF-κB/NLRP3 signaling pathway and limit the release of p-NF-κB, NLRP3, caspase-1, IL-1β, and IL-18, thereby alleviating vascular inflammation and significantly attenuating atherosclerosis in rabbits." (PMID 40373162, 2025). "Notably, TMAO-mediated pathways include endothelial dysfunction, inflammation via NLRP3 inflammasome activation, and cholesterol metabolism disruption, which collectively accelerate atherosclerosis and disease progression." (PMID 40278349, 2025). "This suggests that ferroptosis, in conjunction with pyroptosis (via NLRP3), may regulate atherosclerosis progression, offering insights into potential therapeutic targets for CAD." (PMID 40308274, 2025). "As NLRP3 is already known to promote vascular inflammation and atherosclerosis development, its inhibition from colchicine might explain one of the possible mechanisms involved in cardiac protection from this compound in patients with CCS." (PMID 41010600, 2025). "NLRP3 inhibition may represent an ideal therapeutic target in atherosclerosis by combining anti-inflammasome and anti-proliferative effects in macrophages." (PMID 40956333, 2025). "Overall, the biological actions of colchicine on neutrophils, monocytes, the NLRP3 inflammasome, cytokines, and endothelial function provide a strong mechanistic basis for its potential role in preventing or slowing the progression of atherosclerosis." (PMID 41010600, 2025).
atherosclerosis (continued). "In atherosclerosis, defective ABCA1-mediated cholesterol efflux in macrophages—caused by loss-of-function mutations like p.Glu1282Lys—impairs lipid droplet clearance and promotes NLRP3 inflammasome activation via mitochondrial ROS accumulation." (PMID 40943400, 2025). "Under pathological conditions, NLRP3 inflammasomes induce autocatalysis and activation of caspase-1, leading to the release of proinflammatory cytokines, which are pivotal in the progression of atherosclerosis." (PMID 40791947, 2025). "Activation of the NLRP3 complex at the endothelial level may involve abnormal circulating molecules, such as TMAO, derived from dietary choline associated with atherosclerosis." (PMID 40227195, 2025). "AGEs contribute to the acceleration of the development of atherosclerosis through activation of the NLRP3-ASC inflammasome pathway in a mouse monocyte cell line, and by increasing the level of HMOX1 (a member of the ferroptotic pathway) in primary human aortic endothelial cells." (PMID 40216765, 2025). "Consequently, NLRP3 is considered a key player linking metabolic dysregulation to numerous inflammatory disorders such as gout, diabetes, and atherosclerosis." (PMID 39327931, 2025). "Pyroptosis and NLRP3 inflammasome activation play a crucial role in phenotypic transition or transdifferientiation of VSMCs which result in cardiovascular disorders, including hypertension, atherosclerosis, VC and abdominal aortic aneurysm." (PMID 41335598, 2025). "Notably, the NLRP3 inflammasome plays a pivotal role in various diseases, including Alzheimer’s disease, type 2 diabetes, atherosclerosis, and cancer." (PMID 38543188, 2024). "Pharmacological modulation of NLRP3 inflammasomes has been explored in preclinical models of diseases such as atherosclerosis, gout, and inflammatory bowel disease, providing promising evidence of the potential of NLRP3 inhibitors in the treatment of inflammatory diseases." (PMID 39723212, 2024). "Reports also suggest that NLRP3 inflammasome inhibition might be one mechanism through which metformin mitigates the effects of diabetes on accelerating atherosclerosis." (PMID 38172822, 2024). "Corilagin exerts the anti-atherosclerosis efficacy by inhibiting the Olfr2 signaling pathway in vitro and in vivo, leading to the suppression of NLRP3 inflammasome activation, reducing inflammatory cytokines expression, M1 macrophage polarization, and expression of pyroptosis-related molecule." (PMID 38803504, 2024). "Additionally, neutrophil extracellular traps, cholesterol crystals, ox-LDL cholesterol, and shear stress contribute to NLRP3 inflammasome assembly in atherosclerosis." (PMID 39113913, 2024). "NLRP3 plays a pivotal role in the development of atherosclerosis." (PMID 39857372, 2024). "NAMPT is the gene encoding visfatin, a dual-form ubiquitously expressed, whose functionality encompasses multiple processes related to insulin sensitivity, NDDs, lipid metabolism, atherosclerosis, and pro-inflammatory effects, including NLRP3 inflammasome activation." (PMID 39339745, 2024). "Importantly, several studies have demonstrated that NLRP3 is a potential treatment target in atherosclerosis, as it is involved in pathways that enhance the progression of the disease but are suppressed by NLRP3 inhibitors." (PMID 39194749, 2024). "In addition, animal experiments in mice have found that the role of the NLRP3 inflammasome in atherosclerosis is due to its effector cytokine IL-1β." (PMID 38317229, 2024). "Studies have highlighted how cholesterol accumulation or cholesterol crystal deposits inside or outside cells, triggers the NLRP3 inflammasome in myeloid cells and macrophages, ultimately playing a pivotal role in generating inflammatory lesions within atherosclerosis plaques." (PMID 38762465, 2024).
atherosclerosis (continued). "NF-E2-related 2 (Nrf2) influences the activation of NLRP3 in the presence of cholesterol crystals in the same manner as it does in atherosclerosis, and this finding has been verified by the quantification of IL-1β under conditions of Nrf2 expression and silencing." (PMID 38945951, 2024). "Moreover, in ox-LDL-activated macrophages, by activating AMPK, CTRP9 downregulated the activity and expression of NLRP3, thus preventing atherosclerosis progression." (PMID 38704561, 2024). "Hyperglycemia, as an important risk factor, maybe the reason for the increased expression of NLRP3 in T2DM combined with lower limb atherosclerosis." (PMID 38439031, 2024). "Notably, studies utilizing TET2-deficient mouse models have demonstrated that activation of the NLRP3 inflammasome significantly accelerates atherosclerosis by enhancing inflammatory responses and facilitating plaque formation." (PMID 38803664, 2024). "An NLRP3 deubiquitylation inhibitor or deficiency of Abro1, an essential scaffolding protein in the BRCC3-containing cytosolic complex, suppressed inflammasome activation, neutrophil extracellular trap formation (NETosis), and atherosclerosis in vivo." (PMID 38522750, 2024). "Additionally, Tranilast effectively enhanced NLRP3 ubiquitination and reduced vascular inflammation and atherosclerosis in low-density lipoprotein receptor and apolipoprotein E-deficient mice." (PMID 39144618, 2024). "Additionally, NLRP3 can polarize macrophages toward the M1 phenotype, which exhibit a pro-inflammatory phenotype, exacerbating atherosclerosis." (PMID 39857372, 2024). "Thus, repression of the NLRP3 inflammasome signalling pathway contributes to alleviate diabetes‐related atherosclerosis." (PMID 38774996, 2024). "Endothelial Foxp1 inhibits atherosclerosis by regulating Nlrp3 inflammasome activation." (PMID 38694921, 2024). "In addition to NLRP3, another inflammasome sensor, AIM2, is an active participant in atherosclerosis, and its deficiency reduced pyroptosis and plaque formation." (PMID 38873710, 2024). "Collectively, our findings suggest that SAMB may possess potential therapeutic efficacy against atherosclerosis by exerting anti-inflammatory effects via the modulation of the NF-κB/NLRP3 signaling pathway." (PMID 38839811, 2024). "Following the demonstration of the role of NLRP3 inflammasome activation in atherosclerosis, it has become widely accepted that lysosomal damage by cholesterol crystals represents the major mechanism linking excessive macrophage cholesterol to inflammasome activation in atherosclerosis." (PMID 38522750, 2024). "Elucidating the role of the NLRP3 inflammasome in atherosclerosis can pave the way for the development of novel pharmacological agents aimed at modulating this pathway, thereby potentially mitigating the adverse outcomes associated with myocardial infarction and ischemic cerebral infarction." (PMID 39822376, 2024). "Moreover, SCAP overexpression promotes the translocation of SCAP and NLRP3 inflammasomes to the Golgi apparatus, increasing the activation of the NLRP3 inflammasome pathway and thereby expediting atherosclerosis." (PMID 39224584, 2024). "Hence, oxLDL induces the activation of TRIM64/NF-κB/NLRP3 signaling in macrophages, thereby releasing proinflammatory cytokines, which promote plaque inflammation and atherosclerosis." (PMID 39528464, 2024). "NLRP3 deficiency reduced diet-induced atherosclerosis in female LDL-receptor deficient mice but not in males, a disease also highly dependent on leukocyte recruitment and IL-1β." (PMID 39654901, 2024). "The NLRP3 inflammasome activation is involved in the development of different diseases, including metabolic disorders, autoinflammatory syndromes, gout disease, atherosclerosis, and Alzheimer’s disease." (PMID 39277762, 2024). "These inhibitory effects of olaparib on NLRP3 activity potentially protect against atherosclerosis." (PMID 38335214, 2024).